ENSG00000273974
Gene: Miscellaneous RNA gene on chromosome X (74,280,402 to 74,280,495, forward strand). Ensembl gene ENSG00000273974.
Gene Ontology:
Biological process: positive regulation of gene expression